RN7SKP282 (RN7SK pseudogene 282)
Gene: Miscellaneous RNA gene on chromosome Y (7,324,297 to 7,324,595, reverse strand). Ensembl gene ENSG00000252633.
Homologues: Orthologues: chimpanzee 7SK (96% identical). Paralogues in human: 7SK (81% identical), RN7SKP9 (77% identical), RN7SKP48 (77% identical), RN7SKP174 (76% identical), RN7SKP38 (76% identical), RN7SKP176 (76% identical), RN7SKP187 (76% identical), RN7SKP78 (76% identical), RN7SKP185 (75% identical), RN7SKP217 (75% identical), RN7SKP255 (75% identical), RN7SKP45 (75% identical), and 283 more.